IDO1 (indoleamine 2,3-dioxygenase 1)
Diseases named in the same sentence as IDO1 in open-access papers (continued):
Sharing a sentence is not in itself a finding about the gene and the disease.
tumor (continued). "Further research has revealed that absence of biomarker-guided patient selection may have contributed to limited clinical effect, stressing the need of incorporating kynurenine/tryptophan ratios and tumor IDO1 expression in future trials." (PMID 41035912, 2025). "IDO1, traditionally recognized for catalyzing Trp metabolism, influences tumor progression." (PMID 41332472, 2025). "Specifically, the focus was placed on the immunomodulators and tumor promotors IL-6 and IDO1." (PMID 40699630, 2025). "Among the top 10 upregulated DEPs in tumor conditions were the enzymes IDO1 and LGMN." (PMID 40789452, 2025). "By simultaneously targeting both HCK and IDO1, DAU intervenes in two pathways, one modulating immune cell phenotype and the other regulating ferroptosis susceptibility, thereby creating a synergistic anti‐tumor effect in BLCA." (PMID 41438182, 2025). "The possible reasons could be considered as delivery obstacles such as suboptimal pharmacokinetics, low tumor penetration, and/or the heterogenicity in IDO1 expression across different cancer types and individual patients." (PMID 41129257, 2025). "This functional redundancy implies that tumors may compensate for IDO1 inhibition by upregufiltration and medication penetration in the tumor microenvironment." (PMID 41035912, 2025). "IDO1 is a key immunosuppressor in the tumor microenvironment." (PMID 39934467, 2025). "If these aspects can be improved, the strategy of utilizing IDO1 inhibitors for tumor treatment may yield satisfactory clinical outcomes." (PMID 39934467, 2025). "The intrinsic “on-target” effect of IDO1 catalytic inhibitors in FTC-133 cells is mediated by the stabilization of the IDO1 protein in a non-enzymatic conformation suitable for mediating signal transduction in the tumor cells that results in an adverse effect." (PMID 41262240, 2025). "Since glutamine metabolism supports nucleotide biosynthesis and redox balance, dual nanoparticle-based inhibition of IDO1 and glutaminolysis may prevent tumors from escaping metabolic stress, thereby enhancing anti-tumor efficacy." (PMID 40917745, 2025). "Furthermore, tryptophan metabolism through the kynurenine pathway suppresses anti-tumor immunity, and targeting IDO1 can enhance the efficacy of immune checkpoint inhibitors in advanced cancers." (PMID 39973065, 2025). "Furthermore, tumor cells can secrete indoleamine 2,3-dioxygenase (IDO1), which degrades L-arginine, a critical metabolite for the survival and proliferation of NK cells and T cells." (PMID 40264779, 2025). "Moreover, indoleamine 2,3-dioxygenase (IDO1), an enzyme involved in tumor immunological tolerance, is inhibited by the indole derivative tryptamine." (PMID 40825672, 2025). "Additionally, IDO1 inhibits tumor ferroptosis through its metabolite kynurenine, which promotes GSH synthesis to enhance cellular resistance to ferroptosis." (PMID 41438182, 2025). "In most cancer types, PTEN loss was associated with a higher abundance of CD4+ lymphocytes, M1 macrophages, and FoxP3+ T regulatory cells, along with increased expression of immune checkpoints such as LAG3 and IDO1, indicating an immunosuppressive tumor microenvironment." (PMID 40650023, 2025). "Preclinical evidence suggested that the conversion of the essential amino acid tryptophan (Trp) to immunoregulatory kynurenines (Kyn), generated by the enzymatic activity of IDO1, represents a key mechanism of immune escape within the tumor microenvironment (TME)." (PMID 41262240, 2025). "During an anti-tumor immune response, large quantities of such pro-inflammatory cytokines are secreted and IDO-1 expression could be considered as a representative biomarker of an ongoing anti-tumoral immune activation." (PMID 40475772, 2025). "Instead, these cells were predominantly located in the tumor's peripheral (stromal) regions, which might be due to IDO1 expression." (PMID 40667699, 2025).
tumor (continued). "Thus, it will be important to address in future studies the role of GLI/STAT and IDO1 activity in expansion and accumulation of Treg cells in the tumor immune microenvironment." (PMID 39962447, 2025). "If essential amino acids drop tenfold similar to glucose, IDO1 in the tumor environment could elevate Kyn tenfold, reaching the competitive level for SLC7A5 and effectively activating AhR." (PMID 40103267, 2025). "Both TDO2 and IDO1 play key roles in the metabolism of Trp, and therefore, it is hypothesized that they play a role in tumor immunity." (PMID 40103267, 2025). "The expression of IDO1 can be triggered as a counter-regulatory response to cytokines released by tumor-infiltrating immune cells (such as IL-1β and IL-6), and can also be maintained through intrinsic oncogenic signaling in the tumor." (PMID 40137165, 2025). "Alternatively, IDO-1 in tumor cells could also be induced by Gamma-Interferon (IFN-γ) or other inflammatory mediators." (PMID 40475772, 2025). "Furthermore, IDO inhibition has been shown to reduce the tumor infiltration of MDSCs and inhibit their suppressive character, indicating the crucial role of IDO1-mediated tryptophan metabolite in the suppression of T cell-mediated immune response." (PMID 40096073, 2025). "Previous studies have shown that IDO1 can reduce tryptophan levels and increase tryptophan metabolite levels, primarily kynurenine, in the tumor microenvironment by modulating the tryptophan metabolic pathway, resulting in dysfunction and diminished antitumor effects of CD8 + T cells." (PMID 39934467, 2025). "In this study we evaluated the expression of IDO-1 in NSCLC, both in tumor cells and in tumor immune infiltrate, the prognostic role of IDO-1 expression in terms of OS in different NSCLC sub-populations and its possible correlations between other immune checkpoints in this setting." (PMID 40475772, 2025). "By studying the turnover of IDO1 protein in human tumor cells exposed to various IDO1 catalytic inhibitors, such as epacadostat, linrodostat, and navoximod, we show here that these molecules stabilize a non-enzymatic protein conformation of IDO1, independently of their mechanism of inhibition." (PMID 41262240, 2025). "IDO1, a tryptophan‐metabolizing enzyme, is known to be upregulated in many tumor tissues." (PMID 41438182, 2025). "In the TME, IDO1 not only depletes tryptophan and produces kynurenine to inhibit T‐cell function and promote immune escape, but also influences iron metabolism and ferroptosis sensitivity in tumor cells." (PMID 41438182, 2025). "Furthermore, tumor microenvironment induces imDCs to secret suppressive factors like Il-10, Arg1, Ido1 and Ido2." (PMID 40730800, 2025). "Indoleamine 2,3-dioxygenase 1 (IDO1) is an enzyme involved in the catabolism of the essential amino acid L-tryptophan; it depletes this amino acid and contributes to immune suppression and tolerance in the tumor microenvironment." (PMID 40444100, 2025). "Combining immune checkpoint inhibitors with other immunomodulatory treatments, such as IDO1 inhibitors, could be an effective strategy for treating multiple tumour types." (PMID 39316249, 2025). "Interestingly, our findings also indicate that RIDα/β overexpression in adipocytes promotes an immunosuppressive tumor microenvironment through upregulation of Ido1, Mrc1, and Cd200." (PMID 40526430, 2025). "Perhaps most significantly, it enhanced the antitumor efficacy of engineered T cells while exhibiting favorable selective cytotoxicity (IC50 = 37.4 μM against tumor cells), thereby validating the therapeutic potential of IDO1 degradation in cancer immunotherapy." (PMID 40894232, 2025). "Furthermore, a comprehensive analysis of the tumour microenvironment showed overexpressing of IDO1 and PD‐L1, enrichment of IFN‐γ and PD1 pathways, and a higher intratumour T‐cell infiltrate in NSND compared to SD OSCC patients." (PMID 39737774, 2025).
tumor (continued). "Nonetheless, IDO2 expression was closely aligned with AhR expression and tumour cellularity, while no such association was found between AhR and either IDO1 or TDO2." (PMID 40471422, 2025). "This suggests that these antihypertensive agents may serve as promising anti‐tumor immunotherapy strategies, potentially outperforming existing IDO1 inhibitors." (PMID 39585774, 2025). "Importantly, the MFP of PyMT-RIDad mice also exhibited an enrichment of immunoregulatory molecules such as Ido1, Mrc1, and Cd200, suggesting a shift toward a generally immunosuppressive tumor microenvironment." (PMID 40526430, 2025). "Thus, the activation of the IFN-γ/JAK/STAT1/IDO1 pathway contributes to immune escape in gastrointestinal tumors via its effects on various cell types, including T cells and tumor cells." (PMID 40909948, 2025). "As an important source of energy for many tumor cells, tryptophan (Trp), is easily degraded to kynurenine (Kyn) by indolamine 2,3- dioxygenase 1 (IDO1), which activates the axis of Kyn-AHR to form special suppressive immune microenvironment that promotes tumor growth and metastasis." (PMID 38755645, 2024). "The orally available dual IDO1/TDO2 inhibitor, AT-0174, significantly inhibited tumor progression, reduced tumor-associated macrophages, and reduced expression of immune-suppressive proteins on immune and tumor cells." (PMID 38451784, 2024). "Generally, IDO1 signaling foster a tumor immunological microenvironment that is defective in recognizing and eradicating cancer cells by depleting Trp to generate Kyn, which in turn upregulates the immune‐tolerant cells levels within tumor tissues via activating AhR pathway." (PMID 38884220, 2024). "The threshold for significance was IDO1 staining in >10% of tumor cells." (PMID 39061522, 2024). "Furthermore, we also observed significantly higher expression of IDO1 in primary tumor mast cells (N = 113) than in mast cells located in the metastatic lymph nodes (N = 7)." (PMID 38736462, 2024). "In mice, compared with NSCLC mice, the tumor volume and weight of the IFN-γ group were increased, the expression of CD163, CD206, IDO1, Ki-67 and Bcl-2 in tumor tissue was upregulated, the expression of Bax and C-caspase 3 was downregulated, and apoptosis was reduced." (PMID 38254043, 2024). "In cold tumors, IDO1 immunostaining of tumor cells varied between 0 and 90% (mean: 31%, SD: 34%), and altered immunosuppressed neoplasms displayed IDO1 labeling in 1–80% of tumor cells (mean: 26%, SD: 30%)." (PMID 39061522, 2024). "Considering the involvement of both IDO-1 and HLA-G in feto-maternal tolerance, it is worth exploring whether they cooperate to induce immunosuppression in the context of tumor progression." (PMID 37981615, 2024). "Above all, these evidences indicated that abnormally elevated IDO1 expression of tumor cells could accelerate tryptophan metabolism in OC, which was related to the release of L-kyn enriched EVs." (PMID 38468343, 2024). "Finally, dual inhibition of IDO1/TDO2 in vivo reduced ID8 tumor growth, macrophage infiltration, PD-L1 expression, and extended overall survival in this preclinical model." (PMID 38451784, 2024). "Additionally, immune-regulatory molecules released by tumor cells, such as indoleamine 2,3-dioxygenase 1 (IDO1), can impede effective T cell function." (PMID 38339348, 2024). "Tumor cells can also upregulate and directly secrete the immunosuppressive factor indoleamine 2,3-dioxygenase-1 (IDO1) which increases expression of arginase-1 by tumor cells, causing degradation of L-arginine needed for NK and T cell survival and proliferation." (PMID 38398094, 2024). "Metabolic immune escape markers ADORA2, CD39 and IDO1 were each highly elevated in one tumour." (PMID 35866362, 2024). "However, clinically trialed IDO1 catalytic inhibitors disappointed the expected anti-tumor efficacy." (PMID 38333210, 2024).
tumor (continued). "Moreover, an IDO1 inhibitor restrained endothelial mitophagy, impeding tumor angiogenesis and progression in the orthotopic OC mouse model." (PMID 38468343, 2024). "IDO1 expression can be either triggered as a counter regulatory response to cytokines like IL-1β and IL-6 released from tumor-infiltrating immune cells or maintained through tumor-intrinsic oncogenic signaling." (PMID 38218942, 2024). "Taken together, our findings indicate that increased numbers of M2 TAMs in the tumor foci of EC patients increase IL-10 expression, which stimulates IFN-γ release from CD8+ T cells, leading to IDO1 expression by EC cells and the attenuation of tumor-infiltrating CD8+ T cell responses." (PMID 38540186, 2024). "In hot tumors, 40% and 60% of tumor cells were IDO1 immunopositive." (PMID 39061522, 2024). "Recent evidence indicates that IDO1‐mediated tryptophan depletion may enhance tumor cell recognition by diversifying peptide fragment structures, challenging the notion that tryptophan depletion is the primary cause of immunosuppression." (PMID 39492834, 2024). "IDO1 is expressed on both cancer cells and myeloid cells within the tumor microenvironment, where it elevates the level of kynurenine, an immunosuppressive metabolite, while depleting tryptophan, a vital nutrient for effector cells, including cytotoxic T lymphocytes (CTLs)." (PMID 39346737, 2024). "The current study focused on IDO1 in the context of tumor immunology." (PMID 39312339, 2024). "Thus, the effects of IDO1 inhibitor-mediated modulation of endothelial mitophagy on the immune cells within the tumor microenvironment need to be further explored." (PMID 38468343, 2024). "In addition to the presence of Treg cells in the surrounding TME, an increase in MDSCs and IDO1+ tDCs has also been observed in the neoplasm and axillary lymph nodes of patients with BC." (PMID 39371092, 2024). "In murine models of colon, skin and brain cancer, however, host IDO1 deficiency does not diminish tumor growth, although it modestly enhances the efficacy of immune checkpoint blockade therapies or decreases regulatory T-cell infiltration." (PMID 39211039, 2024). "Therefore, IDO1 has been suggested as a therapeutic target since its inhibition can have a favorable influence on the biological behavior of a tumor as well as its response to established targeted treatment." (PMID 39061522, 2024). "Interestingly, cancer cells in metastatic lymph nodes express significantly (p < 0.0001) higher levels of IDO1 than cancer cells in the primary tumor." (PMID 38736462, 2024). "Moreover, elevated IDO1 expression in tumor cells can induce Treg maturation, enhancing their immunosuppressive effects and promoting immune evasion." (PMID 39227970, 2024). "For in vivo experiments performed with C57BL/6 mice, compared to WT cells treated by TPS, WT cells treated by TPA showed fast tumor growth, evident IDO1 expression, reduced relative Trp concentration, an increased relative [Kyn]/[Trp] ratio, and decreased CD8+T proportion in TIL." (PMID 38540186, 2024). "In cancer cells, FSTL3 prevented the ubiquitination and degradation of c-Myc through interaction with c-Myc, triggered the transcriptional expression of downstream PDL1 and IDO1, and thus blocked the anti-tumor effect of CD8+ T cells and enhanced the infiltration of Tregs." (PMID 38302412, 2024). "In the tumor microenvironment, indoleamine 2,3-dioxygenase 1 (IDO1), a key regulator of T cell function, degrades tryptophan (Trp) to kynurenine (KYN), thereby inhibiting the function of effector T cells and promoting the differentiation and infiltration of immunosuppressive Treg cells." (PMID 39201787, 2024). "Here, we demonstrated that EVs obtained from IDO1 high tumor cells increased L-kyn levels of the endothelial cells, which could further promote the intercellular NAD + levels, implying part of the mechanisms contributing to mitophagy." (PMID 38468343, 2024).
tumor (continued). "However, areas of diffuse immune infiltration had more cytolytic activity as indicated by higher Granzyme B in immune segments, as well as higher tumor expression of targetable checkpoints PD-L1, Tim-3, and IDO1." (PMID 39026018, 2024). "Some studies have reported that under high levels of the microRNA (miRNA) miR-18a, which significantly increases tumor cell development and metastasis and inhibits apoptosis in BC, IDO1 can dampen the expression of NKG2D and natural killer cell group 2D ligand (NKG2DL) in NK cells." (PMID 39371092, 2024). "Consequently, a diverse array of IDO1 inhibitors are presently under development as potential anti-tumor immunotherapies." (PMID 39346737, 2024). "Thus, IDO-1 is abundantly expressed in TNBC, and the levels of IDO-1 are associated negatively with the activation of tumor-infiltrating NK cells." (PMID 37981615, 2024). "Additionally, the tumor group exhibited higher IDO1 expression levels than the normal group (p < 0.01)." (PMID 38780888, 2024). "Thus, our comprehensive data illuminate that tumor-intrinsic FLI1 dampens T cell-mediated immunity by potentiating the IFN-γ-IDO1-Kyn pathway, thereby conferring a survival advantage to the tumor." (PMID 38816360, 2024). "Thus, IDO-1 has emerged as a crucial therapeutic target in the attempt to remodel the immuno-suppressive tumor microenvironment." (PMID 37981615, 2024). "Tumor cells respond to immune cell attacks by expressing IDO1 and recruiting CCL22-positive cells." (PMID 39639005, 2024). "Meanwhile, NLG919 inhibited IDO-1 and reversed the immunosuppressive tumor microenvironment." (PMID 39128942, 2024). "Moreover, high-level expression of IDO1 was found in a large variety of cancer types and correlated with tumour progression and poor prognosis of patients." (PMID 38564046, 2024). "Therefore, our data suggested that the IDO1 inhibitor repressed endothelial mitophagy involved in tumor angiogenesis and development in the orthotopic OC mice model." (PMID 38468343, 2024). "It was found that IDO1 inhibitor RY103 or Incyte inhibited tumor growth." (PMID 38706741, 2024). "IDO1 and TDO2 generated kynurenine in cancer cells, increases kynurenine concentrations in tumors and plasma which is associated with poor prognosis, immunosuppression and tumor progression." (PMID 39450255, 2024). "Thus, loss of genes encoding NF1, TSC1, or TβRII resulted in tumor cell-autonomous inflammatory reprogramming through the activation of the JAK-STAT3/6 pathway and resulted in increased production of IL6 and IDO1." (PMID 38997291, 2024). "Compared with SVCT (SVC tumor), tumor growth was attenuated in VPCT (VPC tumor), STCT (STC tumor), TPCT (TPC tumor), and IFCT (IFC tumor); IDO1 expression was significantly reduced, relative Trp content was high, the relative [Kyn]/[Trp] ratio was low, and CD8+T proportion was upregulated." (PMID 38540186, 2024). "Additionally, 2,4-diamino-6-hydroxypyrimidine (DAHP)-mediated suppression of GCH1 lowered IDO1 expression, inhibited tumor growth, and improved tumor response to PD-1 blocking immunotherapy." (PMID 39371092, 2024). "A high proportion of CD68+ PD-L1+ and CD68+ IDO-1+ TAMs is associated with a poor prognosis, while the presence of PD-L1+ tumor cells, total TAMs, PD-L1- TAMs, or IDO-1- TAMs does not affect the prognosis." (PMID 38779660, 2024). "Increased IDO1 thus enables immune suppression and promotes tumor survival." (PMID 39001353, 2024). "Notably, inhibition of IDO1 in mice with metastatic liver or bladder cancer impeded tumor development." (PMID 39227970, 2024). "This induces IDO1 expression and leads to an immunosuppressive phenotype, and Arg1 and IDO1 may be closely related to tumor immunotherapy." (PMID 39144144, 2024). "In addition, elevated IDO1 expression correlates with tumor progression as well as poor survival in both solid and hematological cancers." (PMID 39211039, 2024).